LAG3 (lymphocyte activating 3)
Diseases named in the same sentence as LAG3 in open-access papers (continued):
Sharing a sentence is not in itself a finding about the gene and the disease.
tumor (continued). "Here authors show that inactivation of the tumor suppressors NF1, TSC1, and TGF-β RII also promotes a non-cell autonomous change in the tumor microenvironment, characterized by inflammatory features and LAG3+ T cell-mediated immune suppression, which are therapeutically targetable." (PMID 38997291, 2024). "Immune checkpoints TIM-3 and LAG-3 can affect anti-tumour responses by inhibiting lymphocyte activity; however, NK cells in the MPE of MPM patients showed high TIM-3 and LAG-3 expression, meaning that TIM-3 and LAG-3 are likely to provide new opportunities for targeted MPE therapies." (PMID 38475858, 2024). "Low expression of LAG3 in tumor tissues might promote the tumor killing effect of T cells, but the number of LAG3+ T cells recruited in tumors was not sufficient to support their anti-tumor effect." (PMID 38604154, 2024). "To investigate the impact of T cell distribution within the tumor microenvironment on patient outcomes, we performed spatial analysis, measuring distances between “Competent” CD8+ (CD8+/PD1−) and CD8+/Exh (CD8+/PD1+ ± LAG3/TIGIT/TIM3+) cells in relation to tumor (CK7+) cells." (PMID 39591972, 2024). "The independent ligands with which LAG-3 interacts are Major Histocompatibility Complex II (MHC-II), Liver and lymph node sinusoidal endothelial cell C-type lectin (LSECtin), and fibrinogen-like protein 1 (FGL1) localized on antigen-presenting cells and tumor cells." (PMID 38893211, 2024). "Based on the fact that several tumor suppressive proteins (IDO1, VISTA, TIM-3, LAG-3 and ICOS) had a higher expression in the tumor-sparse region, we conclude that a wide range of T-cell suppressive features may hamper the expansion of T cells in regions also adjacent to the tumor." (PMID 39001353, 2024). "Analysis of tumour-infiltrating lymphocytes revealed no changes in the expression of memory-associated markers (CD62L and CD44) or exhaustion-associated markers (TIM3, PD1, LAG3, TOX) in CD4+ or CD8+ cells." (PMID 37605057, 2023). "Roughly half (14/25) of the patients with no tumor decrease had detectable LAG-3 expression." (PMID 37857711, 2023). "Additionally, signaling through other expressed immune checkpoints, such as cytotoxic T lymphocyte-associated protein 4 (CTLA-4), lymphocyte-activation gene 3 (LAG3) or T cell immunoglobulin and mucin domain 3 (TIM-3) suppresses the function of immune cells in the tumor microenvironment (TME)." (PMID 37569548, 2023). "Interestingly, CD127 and LAG3 expression in CD8+ lymphocytes, and SIRP expression in monocytes, show a correlation between tumor samples and blood, indicating that peripheral expression of these parameters reliably reflects the composition of tumor infiltrate." (PMID 36900156, 2023). "LAG-3 expression significantly increased in patients with advanced stages (P = 0.036) and recurrence (P = 0.012); however, its expression did not correlate with age (P = 0.613), residual tumor (P = 0.156), or death (P = 0.086)." (PMID 37179337, 2023). "Future therapies to overcome the inhibitory immune checkpoints beyond CTLA-4 and PD-1/PD-L1, such as therapies targeting LAG-3, TIM-3 and TIGIT, may be clinically beneficial since immune exhaustion and subsequent tumor escape remains critical for RCC progression." (PMID 37173966, 2023). "Peripheral, blood-derived samples are more accessible than tumor tissues, so we utilized single cell RNA-sequencing (scRNAseq) of PBMC samples as a highly sensitive orthogonal technique to identify and characterize rare circulating immune cells that express LAG-3." (PMID 37795090, 2023). "CD8 Tex with elevated expression of multiple inhibitory receptors (PDCD1, CTLA4, LAG3, TIGIT, HAVCR2) and Tregs with high expression levels of FOXP3, TIGIT, and CTLA4 were enriched in the ESCC TME, which contributed to tumor immune escape and immunotherapy resistance." (PMID 37187751, 2023).
tumor (continued). "However, PDT alone and PDT with anti-LAG-3 displayed a much weaker tumor growth inhibition, with only one or no CR after treatment, respectively." (PMID 36997666, 2023). "Finally, the inhibitory antibodies without PDT also strongly inhibited tumor growth with several CR in 40–60% of cases, with the exception of anti-LAG-3 alone which did not induce cures, but did inhibit tumor growth compared to controls." (PMID 36997666, 2023). "Although it is not clear whether PD-1 and LAG-3 share the same mechanisms of action, it has been reported synergy between LAG-3 and PD-1 to inhibit effector immune responses, as a high percentage of LAG-3+ and LAG-3− tumor-infiltrating CD8+ T cells expressing PD-1 has been observed." (PMID 38162657, 2023). "Although it is indeed possible that specific similarities or tumor traits that influence how LAG3 influences patient outcomes, we could not identify them at present due to the limited number of studies." (PMID 38041068, 2023). "Moreover, LAG3 also helps maintain CD8+ T cells in a tolerogenic state and has been reported to play an issue role in CD4+CD25+Foxp3+Tregs suppressive function, thus favouring the escape of the tumour from immune surveillance in various human cancers." (PMID 36980527, 2023). "Considering that TIGIT expression is much lower than the expression of LAG-3 or PD-L1 within the tumor, it seems to be challenging to quantify TIGIT expression using nuclear imaging in tumor models with low TIGIT expression, like the MC38 tumor model used in this study." (PMID 37799715, 2023). "Meanwhile, an immunosuppressive TIME promotes tumor growth through various mechanisms, such as depleting tumor-infiltrating T cells, the inhibitory role of immune checkpoint genes like VISTA, TIM-3, and LAG-3, and inhibitory immune cells like Tregs, TAMs, and MDSCs6." (PMID 37777564, 2023). "ADAM2 also restricts expression of the immune checkpoint inhibitors PDL1, LAG3, TIGIT and TIM3 in the tumor microenvironment, which might explain why ex vivo expanded and adoptively transferred cytotoxic T-cells show enhanced cytotoxic efficacy in ADAM2 overexpressing tumors." (PMID 37258521, 2023). "They found that MEK inhibitors not only had a direct killing effect on tumor cells, but also promoted tumor recognition by CD8+ T cells, increased the expression of cytokines such as IFN?, IL12, IL6 and TNFa, and prevented T cell depletion by downregulating PD-L1, CTLA-4, TIM-3 and LAG-3." (PMID 37016422, 2023). "The hallmarks of the immune-regulated group included an inflammatory microenvironment with the infiltration of polyclonal exhausted CD8+/PD-1+/Tim-3+/Lag-3+ tumor-infiltrating leukocytes (TIL) lacking in cytotoxicity, linked to infiltration of dysfunctional DCs." (PMID 37190141, 2023). "Furthermore, KIF18A expression was positively correlated with many common immune checkpoints, including PD-L1, PD-1, CTLA4, TIGIT, HAVCR2, PDCD1LG2, and LAG3, indicating that KIF18A may be a new target for tumor immunotherapy." (PMID 36830695, 2023). "Therefore, tumor cells from peripheral and central tissue microarray (TMA) spots from histologically confirmed PDAC of 68 patients after tumor resection were investigated in terms of expressions of TIM3, IDO, B7H4, LAG3, VISTA, and PD-L1 using immunohistochemistry." (PMID 36768480, 2023). "Moreover, compared to control-treated tumours, the combination of α-PD-1 and PARP14i demonstrated a significant increase of CD4+ and CD8 + T cells expressing surface inhibitory receptors PD-1, TIM-3, and LAG-3." (PMID 37752135, 2023). "Somewhat surprisingly, neither anti-PD1 nor anti-LAG3 improved tumor control achieved by RT+CTLA4i." (PMID 37620372, 2023). "Additionally, based on the spatial arrangement of CD8+PD-1+LAG3- T cells and the density of CD8+PD-1-LAG3-, CD68+STING+, and CD4+FoxP3-PD-L1+ cells, a multi-dimensional marker of tumor-infiltrating immune cells (TIICs) has been successfully developed to predict the response to immunotherapy." (PMID 37190201, 2023).
tumor (continued). "Similarly, administration of PD-1/LAG-3 bispecific antibody also showed a marked increase in the infiltration of CD3+, CD8+, and CD45+ T cells in the TME as well as a significant reduction in tumor progression." (PMID 37055849, 2023). "Our results support the hypothesis that acidity suppresses anti-tumour T lymphocyte function demonstrated by a significant upregulation of inhibitory immune checkpoints TIM-3, LAG-3, and CTLA-4 on the surface of OAC-derived T cells when cultured under low pH conditions ex vivo." (PMID 35708739, 2023). "Priming the tumour with the appropriate neoadjuvant chemoradiotherapy treatment could lead to higher immune infiltrations and higher expression of immune checkpoints, such as PD-1/PDL-1, CTLA4 or emerging new targets: LAG-3, TIM-3, TIGIT or ICOS." (PMID 38155973, 2023). "Therefore, LAG3 regulates the tumor immune system in MPM and could be a potential target for ICIs; LAG3 and PD-1 inhibitors could contribute to a better prognosis of patients with MPM." (PMID 38062416, 2023). "We deduced that it may be possible to reverse T cell dysfunction by intervention in these pathways to revive CD8+ T cells against tumor activity (such as TIGIT, TNFRSF9, CTLA-4, LAG3, PD-1), and this approach maybe represented new strategies for immunotherapy against LUAD." (PMID 36483553, 2022). "Moreover, when PD1, LAG3, and TIGIT were inhibited in tandem with NBTXR3-enhanced radiation, there was also a robust and unambiguous elevation of genes involved in macrophage activation, enhanced trafficking, tumor phagocytosis, and antigen presentation." (PMID 36123677, 2022). "Therefore, we further compared the expression of immune checkpoint genes in tumor tissues of the high SIRGs score group and the low SIRGs score group and found that PD-L1, CTLA-4, HAVCR2, LAG3, TIGIT and PDCD1 were also up-regulated in the high SIRGs score group." (PMID 36052090, 2022). "Interestingly, γδ T cells from HCC patients particularly up‐regulated LAG3, but not other checkpoint molecules, suggesting a LAG3‐mediated exhaustion phenotype of HCC tumour‐infiltrating γδ T cells." (PMID 35538898, 2022). "LAG-3 and PD-1 levels in baseline tumour samples did not correlate with pathologic response." (PMID 36289334, 2022). "Furthermore, MXRA8 was linked to the expression of several immune checkpoints in our work, including PD-1, PD-L1, PD-L2, CTLA-4, TIM-3, and LAG-3; thus, MXRA8 may be involved in tumor immune escape." (PMID 36703779, 2022). "Besides, C1QTNF6 is obviously correlated with many immune checkpoints including LAG3, PDCD1, CTLA4, which suggested that C1QTNF6 may act as a new immune checkpoint for tumor immunity." (PMID 35401204, 2022). "Collectively, these findings support a rationale for combination MAPK signalling and PD-L1 blockade to boost anti-tumour immunity as MAPK-induced upregulation of novel ICs such as TIM-3, LAG-3 and A2aR might represent mechanisms of immune escape or acquired resistance to PD-L1 ICB." (PMID 35228614, 2022). "Perhaps this is not surprising, despite reports that PD-1+ peripheral blood T cell subsets harbor tumor-specific T cell populations, because the expression of PD-1, LAG-3 and TIM-3 alone has not been identified as a predictive biomarker candidate for successful ICB." (PMID 35874702, 2022). "Blockade of LAG-3 in human NK cells does not induce NK cytotoxicity against different tumor types." (PMID 35164813, 2022). "Thus, either LAG-3− Tregs are not all retained within the tumor or LAG-3 expression is downregulated upon egress." (PMID 35472220, 2022). "LAG-3 protein is expressed in tumor-infiltrating lymphocytes but not in other CRC cells." (PMID 35804964, 2022). "Furthermore, PD-1+LAG-3+TILs exhibited a more exhausted phenotype and function than single positive or negative TILs; the dual blockade of PD-1 and LAG-3 resulted in tumor regression." (PMID 35992809, 2022).
tumor (continued). "In mice, single LAG-3 knockout did not lead to development of disease, but it was demonstrated that inhibition or deficiency of Gal-3 activated CD8 T-cells specifically in the tumor microenvironment, suggesting an anti-tumor effect much like PD-L1 inhibition." (PMID 36263134, 2022). "Additional immune checkpoint regulators with emerging clinical relevance include lymphocyte-activation gene 3 (LAG-3/CD223) expressed on activated T cells, NK cells and plasmacytoid DCs, and TIGIT expressed on effector T and NK cells, which binds to CD155 on antigen-presenting cells or tumor cells." (PMID 36175961, 2022). "Furthermore, strong positive correlations were found between levels of FoxP3+Helios− Tregs with CD4+TIM-3+ T cells and CD4+LAG-3+ T cells (r = 0.636, p = 0.002; r = 0.502, p = 0.017, respectively) in tumor tissues but not in PBMCs and NILs." (PMID 35455287, 2022). "Furthermore, a strong positive correlation (r = 0.783, p < 0.0001) was observed between levels of FoxP3+ Tregs and CD4+LAG-3+ T cells in tumor tissues but not in PBMCs and NILs." (PMID 35455287, 2022). "We found that almost all CD8 T cell categories, regardless of LAG3, PD-1, or TIM3 expression, were associated with NLR, indicating that NLR could act as a specific marker for the density of CD8 T cells in primary tumor." (PMID 35892867, 2022). "Moreover, LAG3 is not the only inhibitory checkpoint involved in the pro-tumoral function of tumor-expressed MHC-II." (PMID 36009442, 2022). "However, when exposed to tumor antigens for a long time, the expression of tumor suppressors such as PD-1, CTLA4, TIGIT, TRIM3, and LAG3 in the microenvironment will be significantly upregulated, which will lead to impaired killing function and exhaustion of CD8+ T cells." (PMID 36422531, 2022). "Similarly, we have recently reported that LAG-3 blockade alone induced no survival advantage in mice with established 4T1 or MC38 tumours." (PMID 35265944, 2022). "The function of co-inhibitory receptors, including Tim-3, programmed death-1 (PD-1), cytotoxic T lymphocyte antigen-4 (CTLA-4), and lymphocyte-activation gene 3 (LAG-3), are critical for lymphocyte homeostasis prompting it a novel target for treatment in tumor and infection." (PMID 35250975, 2022). "Moreover, strong positive correlations were observed between levels of FoxP3+Helios+ Tregs with CD4+TIM-3+ T cells and CD4+LAG-3+ T cells (r = 0.767, p < 0.0001; r = 0.749, p < 0.0001, respectively) in tumor tissues but not in circulation or normal tissues." (PMID 35455287, 2022). "Patients whose tumours were LAG3 low (<1%) by IHC did not benefit from addition of Relatimab." (PMID 35054292, 2022). "A study showed that tumor-infiltrating CD8+ cytotoxic T-cells in AML had upregulated inhibitory receptors such as programmed cell death 1 (PD-1), cytotoxic T-lymphocyte antigen 4 (CTLA-4), T-cell immunoglobulin and mucin domain-containing protein 3 (TIM-3), and lymphocyte-activation gene 3 (LAG3)." (PMID 35601490, 2022). "Tumor-specific activation did not induce the expression of PD-1, LAG-3, and TIM-3." (PMID 35328630, 2022). "In summary, MWA dramatically induced the expression of LAG3 on different TILs sub-populatios in TME, and anti-LAG3 treatment in combination with MWA, could significantly suppress tumor development, increase effector CD8+ TILs, and restore the tumor-killing function of exhausted CD8+ T cells." (PMID 36180876, 2022). "Therefore, blocking LAG3 on regulatory T cells may reduce their inhibitory function and lead to a revival of CD8 + tumor-infiltrating lymphocytes activity." (PMID 35279104, 2022). "Furthermore, this study showed that HBV patients who developed HCC had increased expression of both IL-10 by TAMs and the exhaustion markers PD-1, CD152, and Lag-3 by tumor-infiltrating lymphocytes, as compared to non-tumor-infiltrating lymphocytes." (PMID 35454766, 2022). "While Tim‐3 and Lag‐3 expressions were not changed significantly between the two tumor types." (PMID 35948516, 2022).
tumor (continued). "In this study PD-1, TIM-3, LAG-3, CTLA-4 and PD-L2 were significantly upregulated on tumour-infiltrating T cells compared with peripheral circulating T cells in OAC patients, which might reflect a more exhausted T cell phenotype mediated by IC-intrinsic signalling in the tumour microenvironment." (PMID 35366537, 2022). "Human IgGs from four of these collections (i.e., PD-1, PD-L1, Lag-3 and CTLA-4), were characterized and found to specifically bind to their targets with high affinity, to efficiently activate T cell proliferation, to induce cytokine secretion and inhibit in vivo tumor growth." (PMID 34201082, 2021). "Moreover, the inhibition of LAG-3 restored the immune activity of CD8+ T-cells, suggesting that LAG-3 blockade may be a promising strategy for cancer treatment to promote tumor immunity." (PMID 34943817, 2021). "The exhaustion markers PD-1, LAG-3, and TIM-3 were not differentially upregulated over 13 days on BM or splenic localized CD4+ and CD8+ CXCR5 CAR-T compared to SP6 CAR-T cells, thus exhaustion seems to be unlikely involved in loss of tumor control." (PMID 33431832, 2021). "Furthermore, the in vivo administration of anti-LAG-3 mAb in this immunocompetent mouse model suppressed tumor growth and unleashed the antitumor CD8+ T cell-mediated response, supporting the relevant role of LAG-3 as an immune checkpoint and a possible therapeutic target in HNSCC." (PMID 33804419, 2021). "In addition, we investigated that the expression of DHX37 was correlated with several tumor-related immune genes (PD-L1, TIM3, LAG3, TOX, RGS16, and NCOR2), indicating that it may play crucial roles in tumor immune dysregulation." (PMID 33490273, 2021). "It has recently emerged as a novel ligand of LAG3 beyond the classic ligand MHC II and can bind with LAG3 to form a new immune checkpoint pathway independent of PD-1/PD-L1, which results in T cell depletion and subsequent dysfunction, as well as tumor cell escape from immune surveillance." (PMID 34526102, 2021). "Moreover, treatment with relatlimab, a novel anti-LAG-3 blocking monoclonal antibody currently under clinical trial for different solid and hematological malignancies including CLL, restored, at least in part, NK and T cell-mediated anti-tumor responses." (PMID 33925565, 2021). "Moreover, we analyzed the correlation among four-gene signature (FeSig) (BID, TAZ, MT1G, and SLC7A11), downstream hub genes (CPNE7, WNT10B, ADAMTS14, and RUFY4), and immune checkpoints (PD-1, CTLA4, LAG3, and TIGIT) to further discover potential molecular mechanisms of tumor immunity." (PMID 34367965, 2021). "Whereas high LAG-3 expression at the tumor front correlated with microsatellite instability (MSI), this association could not be observed in the tumor center." (PMID 34442393, 2021). "In addition, in animal experiments, more than 30% of MC38 tumor-bearing mice were found to have no tumor formation within 150 days of treatment with anti-FGL1/LAG3 as a monotherapy or in combination with anti-PD-1/PD-L1 therapy." (PMID 34526102, 2021). "Exhausted T cells (LAG3+ PD1+ or TIM3+ PD1+) were also decreased, possibly explaining why Ankrd52 mutation was not eliminated by PD-1 blockade in our tumor mutation profiling." (PMID 34853298, 2021). "The higher frequency of early stage exhausted CD8+ T cells (PD-1+ TIM3+) and later stage exhausted CD4+ T cells (PD-1+ LAG3+) in obese mice may offer an explanation for the faster tumour growth rate in the non-metastatic BC model." (PMID 34445503, 2021). "We found that tumours with G-CSFhigh and CAIX+ phenotypes independently displayed highly significant positive correlations with the presence of intratumoural lymphocytes expressing CD8, PD-1, FOXP3, TIM3, and LAG3, with carcinoma cells expressing PD-L1, and with CD163+ M2 macrophages." (PMID 33804486, 2021).